FTO (FTO alpha-ketoglutarate dependent dioxygenase)
Diseases named in the same sentence as FTO in open-access papers (continued):
Sharing a sentence is not in itself a finding about the gene and the disease.
myocardial infarction (24 papers, 2011 to 2025). Gross necrosis of the myocardium, as a result of interruption of the blood supply to the area, as in coronary thrombosis. "Studies have reported that FTO rs17817449 and rs9939609 play a significant role in the risk of myocardial infarction." (PMID 37238719, 2023). "Conversely, while FTO is downregulated in both human and mouse failing hearts, adeno-associated virus (AAV)-mediated upregulation of FTO attenuated contractile dysfunction in response to myocardial infarction through FTO-mediated demethylation and stabilization of the SERCA2a mRNA transcript." (PMID 38706718, 2024). "HIF1α, activated by myocardial infarction (MI)/hypoxia, bound to the FTO promoter to decrease its expression, causing aberrant m6A modification, while FTO-mediated m6A modification of EPRS, regulated by IGF2BP3, played a key role in cardiac fibrosis after MI." (PMID 39869517, 2025). "A Scottish study of nearly 5000 diabetics of both sexes found that A-allele carriers of the FTO rs9939609 had more than twice the risk of a myocardial infarction or cardiovascular death compared with non-carriers, when adjusted for age, gender, BMI, smoking and history of myocardial infarction." (PMID 21246032, 2011). "Prior research has established that FTO expression is elevated in myocardial infarction models, where it contributes to cardiac homeostasis, structural remodeling, and reparative processes." (PMID 40918160, 2025). "Moreover, variants of the FTO gene were linked with various CVDs, including hypertension, myocardial infarction (MI), acute coronary syndrome, and increased risk of rejection in heart transplant patients." (PMID 39744011, 2024). "Collectively, this study made it clear that FTO suppresses cardiac fibrosis after myocardial infarction via m6A-mediated epigenetic modification of EPRS." (PMID 39538146, 2024). "FTO overexpression also reduced fibrosis and enhanced angiogenesis in mouse models of myocardial infarction." (PMID 37331009, 2023). "Another study showed that FTO promoted endothelial angiogenesis in murine hearts after myocardial infarction, which was beneficial for myocardial repair and remodeling." (PMID 37781923, 2023). "The m6A demethylase, FTO, decreases m6A methylation, thus effectively reducing cardiac fibrosis in myocardial infarction models." (PMID 36384975, 2022). "Overexpression of FTO inhibited cardiac fibrosis, enhanced angiogenesis in the mice with myocardial infarction, and improved heart function by regulating calcium handling." (PMID 34581943, 2022). "In vivo, FTO overexpression improved cardiac function remarkably during the chronic stage of post-myocardial infarction." (PMID 35224032, 2022). "METTL3 and FTO reportedly regulate cardiac fibrosis by mediating the activation of fibroblasts and cardiomyocyte contractile by m6A modifications after myocardial infarction." (PMID 36384975, 2022). "Overexpression of FTO reduces the myocardial fibrosis and enhances the angiogenesis in mouse model of myocardial infarction." (PMID 34489709, 2021). "Susmita demonstrated the importance of FTO-dependent m6A methylation for cardiac systolic function and suggested that the overexpression of FTO reduced fibrosis in a mice model of myocardial infarction (MI)." (PMID 34881240, 2021). "Moreover, influence of FTO on HIF-1α extends beyond cancer, playing a pivotal role in cardiovascular disorders, including ischemic heart disease and myocardial infarction (MI), both of which are associated with hypoxia." (PMID 40102715, 2025). "Furthermore, another study reported that FTO overexpression in mouse models of myocardial infarction reduced cardiac fibrosis and promoted angiogenesis." (PMID 37238719, 2023). "In addition, the expression of FTO is downregulated in myocardial infarction, suggesting that the expression of FTO is generally low in ischemic injury." (PMID 36479246, 2022).
myocardial infarction (continued). "Overexpression of FTO in the myocardial cells of mice subjected to hypoxia or myocardial infarction reduces fibrosis, promotes angiogenesis, and upregulates the expression of myocardial sarcoplasmic/endoplasmic reticulum Ca2+ ATPase 2a (SERCA2a), thereby improving the cardiac systolic function." (PMID 35406663, 2022). "Moreover, adeno-associated virus 9 (AAV9)-mediated myocardial FTO overexpression restores cardiac function in mouse models of myocardial infarction, whereas cardiomyocyte-restricted knockout of FTO mice deteriorates cardiac function." (PMID 35402566, 2022). "FTO has been shown to exert a positive regulatory effect in mouse models of myocardial infarction." (PMID 35406663, 2022). "The FTO is also involved in the pathogenesis of myocardial infarction." (PMID 34489709, 2021). "Regulated expression of FTO was observed in myocardial infarction (MI) and HF patients and respective animal models." (PMID 37331009, 2023).
Anxiety (23 papers, 2014 to 2025). Intense feelings of nervousness, tension, or panic often arise in response to interpersonal stresses. "FTO deficiency is a protective factor against chronic stress and relieves depressive and anxiety-like behaviors in FTO knockout mice." (PMID 40867537, 2025). "Another study found that FTO deficiency increased anxiety and impaired working memory in hippocampus." (PMID 35634463, 2022). "In our study, we demonstrate that the loss of FTO leads to increased anxiety and impairments in working memory in mice." (PMID 30730976, 2019). "However, in another study, the FTO deficiency mice model may reduce anxiety and depressive-like behavior via changes in the gut microbiota." (PMID 37175269, 2023). "Thus, we explored whether the increased anxiety caused by the loss of FTO could alter long-term memory in the Morris water maze and working memory in the eight-arm radial maze tests." (PMID 30730976, 2019). "In animal models, FTO deficiency in the VTA and hippocampus is associated with altered stress reactivity and impaired emotional regulation, implicating m6A methylation in anxiety-like behavior." (PMID 40981072, 2025). "Not only by improving neuroplasticity, but also by alleviating neuroinflammation, FTO has been studied to positively correlate with working memory and anxiety-like behavior." (PMID 39984825, 2025). "Consistent with this study, the downregulation of FTO in the anterior cingulate cortex led to depressive-like and anxiety-like behaviors through the changes in several key components of the BDNF pathway." (PMID 37047192, 2023). "FTO overexpression significantly improved the neurotoxic effects triggered by arsenic, including cortex and hippocampus tissue injuries, deficits in movement coordination, anxiety behavior, and abnormal social behavior." (PMID 39852343, 2025). "Epitranscriptomic regulation appears to influence gene expression within brain circuits critical for anxiety, particularly through the actions of m6A regulators such as FTO in limbic regions including the hippocampus, anterior cingulate cortex (ACC), and ventral tegmental area (VTA)." (PMID 40981072, 2025). "This is why it plays an essential role in the feeling of satiety, as evidence exists of the over-expression of the FTO gene leading to an increase in the intake of foods (especially with high percentages of sugars and fat), as well as feeling of anxiety toward food." (PMID 39057584, 2024). "Moreover, the global knockout of FTO resulted in reduced anxiety-like and depressive-like behaviors." (PMID 37047192, 2023). "FTO may be also be involved in the development of anxiety, as fto−/− mice show increased anxiety-like behavior and hyperactivation of the hypothalamic-pituitary-adrenal (HPA) axis." (PMID 33669361, 2021). "However, the loss of FTO leads to impairment of neuronal differentiation and a processing defect of brain-derived neurotrophic factor (BDNF) within the hippocampus, which increasing anxiety and impairing the working memory." (PMID 36163017, 2022). "According to previous studies, FTO can affect neurogenesis, and the loss of FTO may lead to the change in the BDNF signaling pathway in the hippocampus, resulting in the increase in anxiety and the loss of working memory in mice." (PMID 35634463, 2022). "For instance, FTO knockdown in the ACC induces both depressive- and anxiety-like phenotypes, possibly via downregulation of brain-derived neurotrophic factor (BDNF) signaling." (PMID 40981072, 2025). "Four genes were associated with both treatment outcomes and these symptom dimensions: CGREF1 (anxiety); MCHR1 (neuroticism); FTO and NRXN3 (sleep)." (PMID 39191930, 2024). "In contrast, FTO deletion in the dorsal and ventral hippocampus does not elicit significant anxiety phenotypes, highlighting the context-dependent nature of m6A dynamics in regulating emotional behavior." (PMID 40981072, 2025).
Anxiety (continued). "However, in contrast to these findings, FTO-knockout or Mettl3-knockout in the dorsal and ventral hippocampus did not lead to significant changes in anxiety-like behaviors but increases in fear memory." (PMID 37047192, 2023).
osteoporosis (23 papers, 2011 to 2026). A condition of reduced bone mass, with decreased cortical thickness and a decrease in the number and size of the trabeculae of cancellous bone (but normal chemical composition), resulting in increased fracture incidence. "Due to its important roles in osteoclast-specific genes, FTO is a promising therapeutic target on osteoporosis caused by abnormal bone resorption." (PMID 38020896, 2023). "A previously unknown function of the FTO is the newly reported role in osteoporosis, as in humans FTO in rs1121980 variant is associated with risk of hip fracture." (PMID 37200795, 2023). "Furthermore, more severe bone loss and greater damage to osteoblasts were observed in such mice fed with HFD, implying that individuals carrying the FTO gene mutation are more prone to osteoporosis due to the increased risk of osteoblasts’ apoptosis." (PMID 35883424, 2022). "Collectively, these results indicate that therapeutic inhibition of FTO may able to counteract the bone loss in osteoporosis." (PMID 34496349, 2021). "As an m6A eraser, FTO was associated with osteoporosis phenotypes." (PMID 31998240, 2019). "Decreased FTO expression is correlated with the development of human osteoporosis and osteonecrosis." (PMID 38671918, 2024). "Consistently, the level of FTO is elevated in BMSCs from patients with osteoporosis and ovariectomy (OVX) mouse." (PMID 38665846, 2024). "Meanwhile, OVX-induced osteoporosis in mice with ovariectomies was somewhat mitigated by FTO inhibition." (PMID 38665846, 2024). "In this review, we summarized the influence of FTO-mediated m6A methylation in bone formation and resorption, which helps to explore the pathogenesis of osteoporosis and provide therapeutic strategies based on epigenetics." (PMID 38020896, 2023). "Inhibition of FTO in ovariectomized mice with high FTO expression promoted osteogenesis and alleviated osteoporosis." (PMID 38020896, 2023). "FTO was upregulated in the process of aging and osteoporosis in mice, which promoted the shift of BMSCs to adipocytes rather than osteoblasts and inhibits bone formation through demethylating the mRNA of PPARγ." (PMID 38020896, 2023). "Small molecules which modulate FTO function are potentially novel remedies to the treatment of osteoporosis by adjusting the m6A levels." (PMID 38020896, 2023). "This article reviews the roles of m6A demethylase FTO in regulating bone metabolism and osteoporosis." (PMID 38020896, 2023). "The deficiency of FTO enzymatic activity leads to a marked reduction of BMD and bone mineral content (BMC), similar to that seen in osteoporosis." (PMID 38020896, 2023). "And the role of FTO in osteoporosis in the current study is mainly focused on animal experiments, with fewer research in the population with osteoporosis." (PMID 38020896, 2023). "Given the functional role of FTO in the regulation of skeletal development and bone homeostasis, small molecule compounds targeting FTO can be developed to treat osteoporosis under the precise control of m6A modifications." (PMID 38020896, 2023). "It was demonstrated that FTO was up-regulated during the osteogenic differentiation in human MSCs, by mediating m6A demethylation of osteoporosis biomarker in a YTHDF1-dependent manner." (PMID 37041485, 2023). "Taken together, these results reveal that RNA N6-methyladenosine demethylase FTO promotes osteoporosis through demethylating RUNX2 mRNA and inhibiting osteogenic differentiation." (PMID 34496349, 2021). "In conclusion, our results demonstrate that RNA N6-methyladenosine demethylase FTO promotes osteoporosis through demethylating Runx2 mRNA and inhibiting osteogenic differentiation." (PMID 34496349, 2021). "FTO expression resulted in the increase of the serum concentration of GDF11 in the bone, which was a key risk for osteoporosis." (PMID 31998240, 2019). "They found both BMD and BMC (bone mineral content) were reduced in FTO knockout mice, which was comparable to that seen in osteoporosis." (PMID 31998240, 2019).
osteoporosis (continued). "Additionally, other research has highlighted FTO, YTHDF2 and CBLL1 as diagnostic biomarkers and m6A‐related molecular patterns in osteoporosis." (PMID 39779466, 2025). "Interestingly, METTL3 has been suggested as a potential treatment target in osteoarthritis, whereas FTO has been suggested as a target in osteoporosis." (PMID 39629934, 2025). "Furthermore, knockdown of FTO inhibited NF-κB activation and osteoclast-specific gene expression in an osteoporosis mode." (PMID 41367876, 2025). "Studies reported that FTO was up-regulated in osteoporosis patient and OVX mice." (PMID 37925419, 2023). "Overexpression of FTO in BMSC promoted the progression of osteoporosis by inhibiting osteogenic differentiation through demethylation of Runx2 gene, and inhibition of FTO in ovariectomized mice showed increased bone formation, partially alleviating OVX-induced osteoporosis." (PMID 38020896, 2023). "From this study, FTO appears to play a bad role in the development of osteoporosis." (PMID 38020896, 2023). "Therefore, combining the precise regulation of m6A methylation in bone metabolism with small molecule inhibitors targeting FTO will provide new perspectives and treatment options for osteoporosis." (PMID 38020896, 2023). "FTO mRNA was downregulated in osteoporosis patients and osteonecrosis patients." (PMID 35706030, 2022). "FTO polymorphisms have been investigated in many bone-related diseases, such as hip fracture, osteoporosis and osteoarthritis, but not in ONFH." (PMID 35706030, 2022). "Furthermore, FTO inhibition prevents OVX induced osteoporosis, establishing the indispensability of FTO during the osteogenic differentiation in BMSCs and thereby ensuring skeletal health." (PMID 34496349, 2021). "FTO expression is commonly upregulated in bone marrows during the period of aging and osteoporosis." (PMID 32522250, 2020). "M6A methyltransferase METTL3 and demethyltransferase FTO involves in the delicate process between adipogenesis differentiation and osteogenic differentiation, which is important for the pathological development of osteoporosis." (PMID 31998240, 2019). "Similarly, FTO regulated for BMSCs fate determination during osteoporosis through the GDF11-FTO-PPARγ axis, prompting the shift of MSC lineage commitment to adipocyte and inhibiting bone formation during osteoporosis." (PMID 31998240, 2019). "Taking into account of this biological evidence and our statistical findings, we suggest that FTO might have potential role on BMD or osteoporosis." (PMID 22125610, 2011). "Considering the prior biological findings, we suggest that FTO might be a new candidate for osteoporosis." (PMID 22125610, 2011). "Clinical studies have demonstrated the close connection between variations in the FTO gene and hip fracture risk, confirming that FTO SNPs are correlated with variations in bone mineral density (BMD), potentially establishing them as new biomarkers for osteoporosis." (PMID 39779466, 2025). "Additionally, FTO can directly bind to Runx2, reducing both the m6A methylation level and the overall mRNA expression of Runx2, thereby inhibiting osteogenic differentiation and promoting osteoporosis." (PMID 39779466, 2025). "Moreover, research has demonstrated downregulation of FTO mRNA in osteoporosis patients." (PMID 39136019, 2024). "Furthermore, FTO could also trigger osteoporosis of BMSCs through demethylating Runx2 mRNA and suppressing osteogenic differentiation." (PMID 35445023, 2022). "A study involving 80 women with varying BMD analysed differences in the expression levels of the major m6A regulators, leading to the identification of four potential biomarkers for osteoporosis diagnosis: METTL16, CBLL1, YTHDF2 and FTO." (PMID 39779466, 2025). "Recent released studies has suggested that m6A modification and its regulatory enzymes such as FTO, METTL3 are the key factors for osteoporosis." (PMID 32110378, 2020).
osteoporosis (continued). "Thus, we hypothesize that the FTO gene might be also important for osteoporosis phenotypes." (PMID 22125610, 2011). "FTO and WTAP correct osteoporosis by inhibiting osteoclast differentiation." (PMID 40051055, 2025). "FTO overexpression induces osteogenic differentiation of C3H10T1/2 cells, while the GDF11-FTO-PPARγ axis suppresses bone formation and promotes adipogenic differentiation of osteoporotic bone marrow mesenchymal stem cells during osteoporosis." (PMID 39136019, 2024). "Inhibition of FTO in OVX mice promoted bone formation and alleviated osteoporosis." (PMID 38020896, 2023). "The FTO gene might be a new candidate for BMD variation and osteoporosis in Chinese population, as a candidate genetic marker for peak bone mass acquisition." (PMID 31998240, 2019). "Our findings, together with the prior biological evidence, suggest that the FTO gene might be a new candidate for BMD variation and osteoporosis in Chinese populations." (PMID 22125610, 2011). "Interestingly, FTO expression in the bone is up-regulated during aging and osteoporosis, while the expression of METTL3 is not affected by age." (PMID 32110378, 2020).